EPHB6 (EPH receptor B6)
Diseases named in the same sentence as EPHB6 in open-access papers (continued):
Sharing a sentence is not in itself a finding about the gene and the disease.
cancer (48 papers, 2011 to 2025). A tumor composed of atypical neoplastic, often pleomorphic cells that invade other tissues. "Of these overlapping genes, several have been implicated in cancer migration/invasion or metastasis, including EPHB6, AGR2, RAB37, CST1, and B4GALNT3." (PMID 34270616, 2021). "The immature T-cells, especially in subtypes AB/B1, had higher EphB6 H-score than carcinoma-associated mature lymphocytes (p < 0.001); carcinomas had higher lymphocytic EphB1 H-score (p = 0.026)." (PMID 34943502, 2021). "The top association was between mutated forms of EPHB6, a gene previously linked to tumor invasiveness, and resistance to paclitaxel, a chemotherapy drug used to treat a range of different cancers." (PMID 31160603, 2019). "The present study investigated the effect of the EPHB6 mutation on paclitaxel resistance in various cancer types." (PMID 31160603, 2019). "In the present study, a previous knowledge-based CCLE data analysis predicted that the EPHB6 mutation induces paclitaxel resistance in cancer cells, which was validated experimentally." (PMID 31160603, 2019). "Here, the recapitulation of pharmacogenomic data revealed that the mutation of EPHB6 is associated with paclitaxel resistance in cancer cells." (PMID 31160603, 2019). "The present results suggest a novel mechanism underlying paclitaxel resistance in cancer patients and identify EPHB6 as a novel therapeutic target and/or biomarker for paclitaxel resistance in cancer patients." (PMID 31160603, 2019). "Studies in candidate cancer genes including EPHB6/TRPV6 found two SNPs in EPHB6/TRPV6 marginally associated with survival in CRC." (PMID 29299148, 2017). "Loss of EphB6 was associated with advanced tumor stage, cancer progression and tumor vasculature in several types of human cancers." (PMID 27145271, 2016). "Loss of EphB6 is associated with angiogenesis and tumor vasculature in several types of human cancer." (PMID 25789021, 2015). "The results revealed that low expression of EphB6 was significantly associated with a high volume (≥4 cm3) of cancer (P=0.015) and advanced pathological stage (pT3) (P=0.0007)." (PMID 25789021, 2015). "Eb6Mab-3, established by the CBIS method, could be valuable for analyzing the EphB6-associated cellular functions and has potential applications in diagnosis and treatment with specificity and high affinity for cancer cells." (PMID 40065768, 2025). "This supports the idea that perturbation of EphB6 clustering could serve as an underlying mechanism that drives cancer invasion." (PMID 38627519, 2024). "The role of EphB6 in cancer is still a matter of debate, and even though the underlying mechanism through which EphB6 influences cancer progression remains unclear, the existing body of evidence leans toward its role in suppressing metastasis." (PMID 38627519, 2024). "However, although recurrent mutations in EPHB6 are observed in various types of cancer, the effect of EPHB6 mutations on drug resistance remains to be investigated." (PMID 31160603, 2019). "In conclusion, the present results suggest that the EPHB6 mutation promotes cancer cell proliferation and migration/invasion and induces CAM-DR, and these effects are mediated by the stabilization of EPHA2 and the activation of downstream JNK/CDH11/RhoA/FAK signaling." (PMID 31160603, 2019). "This indirectly suggested that SRC overexpression might act as an essential compensatory mechanism for the loss of EPHB6 in cancer cells, indicating that the SL interaction of EPHB6 and SRC may represent a promising therapeutic target." (PMID 27418135, 2016). "Further, the information with respect to somatic mutations in EPHB6 and ESR1 in OSCC is also inadequate; while pooling of these mutations is well documented in other malignant tumours." (PMID 40457841, 2025).
cancer (continued). "Concerning the poorly characterized Class 2 pseudokinase receptors EPHA10 and EPHB6 whose expression is often disregulated in cancer, their ability to bind kinase inhibitors offer opportunities for future therapeutics." (PMID 38773263, 2024). "Briefly, our study elucidated the expression patterns of Eph receptors and EFN ligands pan-cancer, and identified a novel biomarker of EPHB6 as a potential effective therapeutic target to improve the immunotherapy response of BLCA." (PMID 37637034, 2023). "There is increasing evidence that points to the dysregulation of EPH receptor B6 (EPHB6) in various cancers." (PMID 37101747, 2023). "This study comprehensively investigated the immunological effects of Eph receptor/EFN ligand family genes pan-cancer, and specially identified the immunosuppressive role of EPHB6 in BLCA." (PMID 37637034, 2023). "For the first time, it was identified that EPHB6, a previously recognized inactive kinase receptor, had a significantly relation with immunomodulatory genes expression in most types of cancer." (PMID 37637034, 2023). "Thereafter, the role of EPHB6 in the immune microenvironment, anti-cancer immunity, and as correlate of immunotherapy response of BLCA was investigated." (PMID 37637034, 2023). "The role of EphB6 in cancer is quite complex, as it not only downregulates and suppresses aggressiveness in multiple malignancies and cancer cells, but also supports tumor initiation in colorectal and breast cancers." (PMID 33770085, 2021). "We found a molecule, called EphB6, that supports the persistence of disseminated dormant cancer cells thanks to the activation of a cellular process, the lysosomal-flux, that is a central hub for nutrient sensing and recycling of the cell." (PMID 33802447, 2021). "Our data provide evidence that EphB6 is a key factor in the crosstalk between disseminated dormant cancer cells and the lung parenchyma and that the TFEB-lysosomal pathway plays an important role in the persistence of DDCCs." (PMID 33802447, 2021). "For example, several studies of EphB6 in human breast and lung cancer cells identify a direct effect of EphB6 on the activation of Erk kinases, whereas other studies suggest that EphB6 modulates Akt signaling in a more complex manner." (PMID 34360976, 2021). "On the other hand, EPHB6 expression was down-regulated in neoplastic tissues, in accordance with its tumor-suppressive properties observed in other cancers." (PMID 34445116, 2021). "Examples include Eph‐dependent signalling in endocrine and immune systems as well as in cancer cell proliferation, where links between EphB6 and EphA10 and canonical kinases such as EphB4, EphB1 and Src‐family kinases have been established." (PMID 32053275, 2020). "EphB6, an Eph receptor that doesn’t have tyrosine kinase activity, was reported to be expressed in some human cancers." (PMID 32993565, 2020). "To assess EPHB6 effect on tumour initiation, we injected mice with decreasing doses of cancer cells." (PMID 29700392, 2018). "To examine if EPHB6 supports cancer drug resistance, we treated mice with MDA-pc3 or MDA-B6-M tumours with a DNA-damaging drug, doxorubicin, which is frequently used in TNBC therapy." (PMID 29700392, 2018). "Although the actions of some EphB receptors in cancer seem contradictory, EphB6 downregulation has been consistently correlated with enhanced aggressiveness and invasiveness in melanoma, neuroblastoma and non–small cell lung cancer." (PMID 27145271, 2016). "This also explains well the ability of EPHB6 to protect cancer cells from shRNA-induced silencing of SRC or src knockout observed in our work." (PMID 27418135, 2016).
cancer (continued). "Our data demonstrate the role of EphB6 in cancer-related signal transduction pathways and provide novel insight into mechanisms of CRC tumorigenesis." (PMID 27145271, 2016). "Some of the hits were also associated with other cellular compartments, including nucleus and cytoplasm, which reflected the complexity of the network of EPHB6 functional interactions in cancer cells." (PMID 27418135, 2016). "Microarray data and pathway analysis of differentially expressed genes provided insight into possible EphB6-regulated mechanisms promoting tumorigenesis and cancer progression." (PMID 27145271, 2016). "The association between tumor characteristics (including Gleason score, cancer volume and pathological stage) and EphB6 or PCNA expression were evaluated." (PMID 25789021, 2015). "In contrast, tumor suppressive functions of EphB6 have been proposed in various cancers." (PMID 40065768, 2025). "Further investigation is necessary to clarify these opposing functions of EphB6 in cancer." (PMID 40065768, 2025). "EphB6 was shown to reduce motility and invasion of breast and lung cancer cells." (PMID 38341842, 2024). "Previous studies have suggested that EPHB6 may have both oncogene and tumor suppressor roles in different types of cancer." (PMID 37637034, 2023). "In the EPHB6-high expression group, the activities of steps 1, 4, and 7 in the cancer immunity cycle were weakened from the perspective of molecular functions, which implies that the activities of cancer cell antigen release and immune cells tracking tumor cells were restricted." (PMID 37637034, 2023). "As a result, the relationship that exists between EPHB6 and the immune cells may be partially responsible for the anti-cancer impact that it has." (PMID 37101747, 2023). "The ephrin receptor, EphB6, functions as a tumor suppressor in cancer development." (PMID 33962392, 2021). "We then turned our attention to the role of EphB6 in dormant cancer cells." (PMID 33802447, 2021). "The present results suggest that the EPHB6 mutation and its downstream EPHA2/JNK/CDH11/RhoA/FAK signaling axis are novel diagnostic and therapeutic targets for overcoming paclitaxel resistance in cancer patients." (PMID 31160603, 2019). "As EMT is associated with increased cell motility and reduced contacts between cancer cells, our observations indicate that EPHB6 could antagonise this process." (PMID 29700392, 2018). "Furthermore, microarray data and pathway analysis of differentially expressed genes provided insight into possible EphB6-regulated mechanisms of tumorigenesis and cancer progression." (PMID 27145271, 2016). "Our model also provides a rational explanation for why in multiple cancer types, malignant tumours tend to reduce EPHB6 expression, since a decrease in EPHB6 levels should improve survival of cancer cells by protecting them from immunoelimination mediated by DR5 activation." (PMID 27788485, 2016). "In addition, our observations also highlight the potential for EPHB6 to be used as a novel target for cancer therapy." (PMID 27788485, 2016). "However, considerably more research was focused on EphB6 involvement in cancer." (PMID 38341842, 2024). "Finally, our findings also suggest that the EPHB6 receptor itself may represent a promising target for cancer therapy, since EPHB6 and DR5 co-activation should support more efficient elimination of cancer cells." (PMID 27788485, 2016). "Additional genes upregulated in carcinoma patients as a result of CARD11 overexpression included MTMR2, EMB, EPHB6, and CPEB4, which are related to various cancer-related processes." (PMID 39408697, 2024). "Carcinoma patients showed a dramatic increase in the expression of MAPK8IP2 in CARD11+ carcinoma patients alongside other cancer-related genes, including EMB, EPHB6, and CPEB4." (PMID 39408697, 2024). "There were some RTK genes (EPHB6, EPHA1, EPHB3, FGFR4, PDGFRB, and FLT4) showing amplification in cancer cells." (PMID 32038722, 2019).
cancer (continued). "Expression microarrays using mRNAs and lncRNAs isolated from EphB6-overexpresssing IMCE and control cells revealed a large number of dysregulated genes involved in cancer-related functions and pathways." (PMID 27145271, 2016). "Among the numerous targets of several miRNAs affected in an EphB6-dependent manner, interaction of Trib with FOXO assumes cancer related significance." (PMID 21811619, 2011). "We present here the relationship between miRNAs and EphB6 expression status of MDA-MB-231 cells and the biological relevance of these changes for cancer cell phenotypes." (PMID 21811619, 2011). "Additionally, differences were observed in NR3C2, ATR, ALK, EPHB6, SPEN in intermediate cells (I-1 to I-8) relative to the cancer cells." (PMID 35951662, 2022). "Since earlier work shows that EPHB6 often executes its responses through interactions with other EphB receptors, we examined if it also interferes with DR5-induced apoptosis in cancer cells." (PMID 27788485, 2016). "Interestingly, crosstalk between EphB6 and EGFR cooperates in cancer progression." (PMID 40065768, 2025). "EphB6 is involved in cancer pathology despite lacking kinase activity." (PMID 40065768, 2025). "In this study, a pan-cancer analysis was initially performed to reveal the relationship between the Eph receptors and EFN ligands expression and immunoregulatory factors and identified inactive kinase EPHB6 which shaped a cold immune microenvironment and promoted the immune escape in BLCA." (PMID 37637034, 2023). "Moreover, EPHB6 does not increase the sensitivity of tumoursphere cells to bortezomib, a cancer drug that acts as a proteasomal inhibitor and should not directly depend on the proliferative activity." (PMID 29700392, 2018). "Our investigation also indicates that it could be beneficial to support EPHB6 activity in TNBC tumours, when using conventional DNA-damaging treatment, as this would improve tumour elimination, while also suppressing invasive properties of cancer cells." (PMID 29700392, 2018). "EphB6, an unusual Eph receptor without catalytic capacity due to alterations within its kinase domain, may act to suppress cancer aggression." (PMID 27145271, 2016). "The identified membrane proteins serve as receptors (EPHB6, ACKR1, and EDNRB) or adhesion molecules (EPCAM) and may enhance antitumor immunity (TENM2 and CLEC‐10A); thus, they may contribute to enhanced mEHT‐induced cancer destruction through regulating the TME related immune response." (PMID 38217262, 2024). "Notably, pan-cancer analysis showed that EPHB6 could not exert the similarly cold immune effects in most other types of cancer; hence, anti-EPHB6 immunotherapy might be suitable for patients with BLCA only, but it requires further clinical investigations." (PMID 37637034, 2023).
tumor (47 papers, 2006 to 2026). "On the other hand, two studies underline the protective role of EPHB6, as its expression was found to be downregulated in tumor cells, being negatively associated with tumor stage, LN metastasis, and a poor level of differentiation." (PMID 34445116, 2021). "Taken together, these results suggest that the mutation of EPHB6 induces paclitaxel resistance in tumor cells." (PMID 31160603, 2019). "Our previous work shows that EPHB6 is synthetic lethal with Src, and TNBC cells and tumours with EPHB6 deficiency are effectively eliminated by Src-inhibiting compounds." (PMID 27788485, 2016). "Mutations in the EphB6 gene that promote tumor metastasis have been identified in NSCLC patients." (PMID 40065768, 2025). "Loss of EphB6 brings tumor malignancy and poor prognosis [23,]." (PMID 40065768, 2025). "The EphB6 expression was detected in four GC cell lines, its overexpression was associated with tumor differentiation while its underexpression was associated with lymph node metastasis and tumor stage." (PMID 39839790, 2024). "The loss of EphB6 protein was associated with higher tumor grade and TNM stage." (PMID 27887627, 2016). "Loss of the kinase-dead EPHB6 is associated with advanced tumor stages and cancer progression." (PMID 23226491, 2012). "In clinical thyroid malignant lesions from patients, the higher expression of EphB6 and EphB4 has been observed compared to benign ones and correlated with tumor size." (PMID 40065768, 2025). "Low EphB6 expression is associated with poor TNM stage and tumor grade in ovarian serous carcinoma and neuroblastoma." (PMID 40065768, 2025). "Quantitative PCR was performed and revealed that EphB6 mRNA level was significantly higher in all 17 NF-PitNETs samples compared to human normal pituitary and notably was correlated with the tumor size." (PMID 38341842, 2024). "Based on these features, the following experiments mainly focused on investigating the role of EPHB6 and tumor immunology in BLCA." (PMID 37637034, 2023). "In contrast, EphB6 was shown to be tumour suppressive, which correlated with its lower expression in metastatic compared to nonmetastatic NSCLC." (PMID 33430066, 2021). "Despite its beneficial influence in many neoplastic diseases, EPHB6 seems to promote tumorigenesis in the breast, as its expression was reported as higher in malignant tissues and was correlated with reduced OS." (PMID 34445116, 2021). "HCI-010 tumours are EPHB6-positive and there, EPHB6 action mimicked responses that we initially observed in TNBC cell lines." (PMID 29700392, 2018). "Remarkably, EPHB6 also suppresses tumour drug resistance to DNA-damaging therapy, probably by forcing TICs into a more proliferative, drug-sensitive state." (PMID 29700392, 2018). "Since TNBC is mostly treated with compounds acting on fast-propagating cells, including doxorubicin and taxane derivatives, our model predicts better relapse-free survival of TNBC patients with high EPHB6 expression in their tumours." (PMID 29700392, 2018). "Despite accumulating evidence, suggesting an important tumour-suppressing role for EPHB6, our understanding of its function in malignancy is far from complete." (PMID 29700392, 2018). "In line with its ability to trigger propagation of TICs, EPHB6 accelerates tumour growth, potentiates tumour initiation and increases TIC populations in xenograft models of TNBC." (PMID 29700392, 2018). "Consistent with EPHB6 action in TNBC cell lines, EPHB6 silencing reduced growth rates in saline-treated tumours, while increasing tumour resistance to doxorubicin." (PMID 29700392, 2018). "EphB6 has been shown to be prognostic indicator for NSLC, and deleterious mutations in this protein have also been characterized in primary tumor specimens obtained from NSLC patients." (PMID 29682554, 2018). "To fill this knowledge gap, we analysed the TCGA gene expression database, assessing EPHB6 status in 530 tumours and 62 normal samples." (PMID 29700392, 2018).